LINC02692 (long independently transcribed non-coding RNA 2692)
Synonyms: formerly C9orf141; PRR31
Gene: Long non-coding RNA gene on chromosome 9 (136,969,243 to 136,972,890, forward strand). Ensembl gene ENSG00000198454.
Diseases named in the same sentence as LINC02692 in open-access papers:
LINC02692 is named in the same sentence as 1 disease in open-access papers, as found by Europe PMC text mining. Sharing a sentence is not in itself a finding about the gene and the disease.
LINC02692 shares sentences with these, for which no sentence is quoted: cancer (1 paper).